PDGFRA (platelet derived growth factor receptor alpha)
Diseases named in the same sentence as PDGFRA in open-access papers (continued):
Sharing a sentence is not in itself a finding about the gene and the disease.
heart failure (5 papers, 2019 to 2024). Inability of the heart to pump blood at an adequate rate to meet tissue metabolic requirements. "Consistently with the mouse heart data, immunofluorescence staining data showed that the expression of VIM, PDGFRA and POSTN were significantly increased in the heart failure group compared with the normal heart." (PMID 36805782, 2023). "In addition, immunofluorescence staining demonstrated elevated expression levels of fibroblast markers (such as POSTN and PDGFRA) and FABP4+ fibroblasts (FABP4 + POSTN+ and FABP4 + PDGFRA+) in the heart failure group compared to those in the control group." (PMID 39198543, 2024). "Systemic administration of HMGB1 induced angiogenesis and reduced fibrosis by recruiting PDGFRα+ mesenchymal cells from the bone marrow, suggesting that HMGB1 administration might be a new therapeutic approach for heart failure after MI." (PMID 32275672, 2020).
Hypertension (5 papers, 2012 to 2025). The presence of chronic increased pressure in the systemic arterial system. "Second, Lenvatinib, a multi-targeted tyrosine kinase inhibitor (TKI), obstructs VEGF receptors (VEGFR1-3), FGFR, and PDGFRα, leading to hypertension (35% compared to 18% in dual therapy), proteinuria, and hepatic dysfunction via vascular destabilization and metabolic dysregulation." (PMID 40777037, 2025). "In univariate analysis two factors significantly correlated with shorter PFS and OS that were: tumor genotype: exon 11 KIT or PDGFRA mutation (p = 0.04 and p = 0.04, respectively), and absence of arterial hypertension during sunitinib therapy (p = 0.0001 and p = 0.001)." (PMID 22439647, 2012).
Insulin resistance (5 papers, 2020 to 2025). Increased resistance towards insulin, that is, diminished effectiveness of insulin in reducing blood glucose levels. "Other studies have suggested that the activation of the PDGFRα pathway in adipose tissue suppresses Wnt/β-catenin signaling during the final stages of adipogenesis, which has been linked to an early onset of insulin resistance." (PMID 37242132, 2023). "Thus, although Pdgfrα-Cre mediated knockout of Ahr appeared to offer some protection against HFD-induced insulin resistance at certain time points, the overall effect on insulin sensitivity was not considered significant." (PMID 32730300, 2020). "This could be because Ahr knockout in other tissues besides those that express Pdgfrα are important for protection against insulin resistance." (PMID 32730300, 2020). "While the results of our studies with the Pdgfrα-Cre mediated knockout mice were suggestive of protection against insulin resistance, the effects were not overtly significant." (PMID 32730300, 2020).
liver cirrhosis (5 papers, 2014 to 2025). "As we reported in a previous study, the cell proportion of PDGFRα+ CAFs was high in the subset of patients with liver cirrhosis (before hepatocarcinogenesis)." (PMID 39827226, 2025). "Changes in the expression profile were observed between RGS5+ CAFs and PDGFRα+ CAFs in the pseudotime trajectory, GO enrichment analyses of BP terms revealed that PDGFRα+ CAFs from patients with liver cirrhosis and HCC were enriched mainly in functions related to the inflammatory response." (PMID 39827226, 2025). "In addition, stimulation of PDGFRα expression by excessive production of PDGF-CC induces liver cirrhosis and HCC in PDGF-C transgenic (Tg) mice." (PMID 30509307, 2018). "In our study with human HCC samples, tumor site PDGFRα expression does not necessarily associated with the underlying liver cirrhosis and PDGFRα expression in the adjacent non-tumor sites." (PMID 28465473, 2017). "On the other hands, expression of PDGFRα and αSMA in tumor site did not affected by underlying liver cirrhosis." (PMID 28465473, 2017). "We evaluated whether PDGFRα expression in tumor sites were associated with underlying liver cirrhosis or non-tumor site PDGFRα expression." (PMID 28465473, 2017). "However, the increased PDGFRα expression in HCC subsets in the absence of background liver cirrhosis suggests that abnormal hepatocytes overexpress PDGFRα." (PMID 30509307, 2018). "Patients with strong PDGFRα expression on HCC showed similar gender ratio, higher proportion of patients with AFP >200 ng/mL, and lower portion of patients with liver cirrhosis compared with patients with either no or moderate PDGRα stain." (PMID 28465473, 2017).
liver disease (5 papers, 2014 to 2025). "Consequently, our findings provide novel evidence suggesting that an increased interaction of PDGFC and PDGFRA between stellate cells with cholangiocytes, as well as myeloid cells, is associated with liver disease progression and enhanced fibrotic damage." (PMID 38768139, 2024). "Multivariate analysis test suggested that preoperatively elevated AFP above 200 ng/mL, existence of macrovascular invasion, having underlying liver diseases due to alcohol abuse were associated with poor survival in addition to strong PDGFRα positivity on tumor sites." (PMID 28465473, 2017). "If PDGFRα expression were to be associated with the status of underlying liver disease, it could have been suggested that characteristics of HCC were to be dependent on the background liver condition." (PMID 28465473, 2017). "Here, we show that platelet-derived growth factor receptor α (PDGFRα) is expressed by human HSCs, and PDGFRα expression is elevated in human liver disease." (PMID 24667490, 2014). "In addition, and consistent with the notion that PDGFRα regulates the liver’s response to injury, patients with liver disease have elevated expression of PDGFRα and PDGFRβ." (PMID 24667490, 2014). "Using a green fluorescent protein (GFP) reporter mouse strain, we evaluated the role of PDGFRα in liver disease in mice and found that mouse HSCs express PDGFRα and expression is upregulated during carbon tetrachloride (CCl4) induced liver injury and fibrosis injection." (PMID 24667490, 2014). "This study aimed to investigate whether PDGFRα expression in HCC is associated with the status of the underlying liver disease by assessing PDGFRα expression on tumor and matching non-tumor sites." (PMID 28465473, 2017). "Moreover, expression of PDGFRα/β, TGF-β1 and ET-1, which are related to HSC activation, development of fibrosis, and portal hypertension, were upregulated in both genotypes in response to LCA." (PMID 31752395, 2019).
lung squamous cell carcinoma (5 papers, 2014 to 2023). "Importantly, the data also demonstrated the potential activation of STAT3 by a number of upstream receptor tyrosine kinase signaling pathways found to be recurrently amplified in squamous cell lung carcinoma, including PDGFRA and/or KIT, EGFR, and FGFR1." (PMID 25573684, 2015).
meningioma (5 papers, 2013 to 2025). A generally slow growing tumor attached to the dura mater. "In this study, we evaluated the efficacy of the ponatinib in MGM cells and found that ponatinib demonstrated potent anti-meningioma effects in vitro and in vivo presumably through PDGFRA/B inhibition and mitochondrial dysfunction." (PMID 34885009, 2021). "Interestingly, PDGFRA expression on meningioma cells is rare and might not play an important role in meningioma pathology." (PMID 34885009, 2021).
myopia (5 papers, 2011 to 2025). "They found that polymorphisms in the mechanistic target of rapamycin kinase (MTOR) and platelet-derived growth factor receptor alpha (PDGFRA) genes were associated with different degrees of myopia severity." (PMID 40657400, 2025). "We thus undertook a candidate SNP approach with the identified SNPs to investigate the possible association between PDGFRA and (i) the onset of high myopia; (ii) the refractive error as a quantitative trait." (PMID 22144915, 2011). "It is confirmed that MTOR and PDGFRA are related to the severity of myopia, possessing gene-gene interaction." (PMID 38660258, 2024). "Researchers indicate that PAX6 rs644242, ZC3H11B rs4373767 and BICC1 rs7084402, VIPR2 rs885863 and rs6979985, ZMAT4 rs7829127, TNKS rs4840437 and rs6989782, PDGFRA rs2114039, SOX2 rs4575941, FGF10 rs339501, rs2973644, and rs 79002828 are associated with severe myopia (moderate and extreme myopia)." (PMID 38660258, 2024). "We also evaluated the roles of RASGRF1 rs6495367, PDGFRA rs6554163, and PTPRR rs11178469 in myopia in a southern Chinese Han population." (PMID 34122509, 2021). "By revealing the potential relationships between genes and miRNAs correlated with PDGFRA, RASGRF1, and PTPN5, this study may shed new light on myopia at the molecular level." (PMID 34122509, 2021).
renal fibrosis (5 papers, 2014 to 2024). A final common manifestation of a wide variety of chronic kidney diseases characterized by glomerulosclerosis and tubulointerstitial fibrosis. "Contrary to MST1/2 deficiency in PDGFRα+ cells or tubule cells, MST1/2 deficiency in macrophage inhibited M2 accumulation and fibrosis in the obstructed kidney of mice, revealing the role of MST1/2 in different cells on renal fibrosis." (PMID 38250155, 2024). "Furthermore, specific deletion of c-Abl in ECM-producing PDGFRα+ mesenchymal cells significantly mitigated renal fibrosis." (PMID 38689280, 2024). "Overall, the increased expression of c-Abl in mouse fibrotic kidneys and its enrichment in ECM-producing PDGFRα+ mesenchymal cells and α-SMA+ myofibroblasts strongly suggest a potential role for c-Abl in the pathogenesis of renal fibrosis." (PMID 38689280, 2024). "PDGFRα+ mesenchymal cells in the fibrotic kidneys of mice consist of fibroblasts and myofibroblasts, and FMT is a crucial process in renal fibrosis." (PMID 38689280, 2024). "Next, the expression of RACK1 was significantly increased in fibrotic kidneys compared to that in CL kidneys and was colocalized with PDGFRα+ mesenchymal cells and αSMA+ or Col1a1+ myofibroblasts in fibrotic kidneys, implying that RACK1 may play a crucial role in FMT during renal fibrosis." (PMID 38689280, 2024).
spindle cell tumors (5 papers, 2016 to 2024). "KIT mutations were predominantly found in spindle-cell tumors (72%), while PDGFRA (both D842V and non-D842V) were primarily observed in purely epithelioid or mixed tumors (96%) (p < 0.001)." (PMID 39199677, 2024). "KIT mutations were predominantly found in spindle-cell tumors, whereas PDGFRA mutations were more common in epithelioid and mixed tumors (p < 0.001)." (PMID 39199677, 2024). "We report a case of a primary cardiac spindle cell neoplasm with concerning histological features and a rare PDGFRA::USP8 gene fusion in a 3 year old boy." (PMID 38401149, 2024). "The differential diagnosis should consider other spindle cell tumors, and molecular testing for KIT and PDGFRA mutations is essential for both diagnosis and therapeutic planning." (PMID 39559661, 2024). "In summary, we report a case of pediatric primary cardiac unclassified spindle cell neoplasm with a very rare PDGFRA::USP8 gene fusion." (PMID 38401149, 2024). "We report a case of a pediatric primary cardiac spindle cell neoplasm with a PDGFRA::USP8 gene fusion in the right ventricle, arising from the inlet part of the ventricular septum." (PMID 38401149, 2024). "PEComa should be included in the differential diagnosis of PDGFRα-positive spindle cell tumors in the wall of the gastrointestinal tract." (PMID 27842558, 2016). "Pathology revealed an unclassified spindle cell neoplasm with a PDGFRA::USP8 gene fusion." (PMID 38401149, 2024).
viral infection (5 papers, 2017 to 2025). "Although not essential for hCMV entry into fibroblasts, the combined presence of NRP2 and PDGFRA may increase susceptibility to viral infection." (PMID 40163451, 2025). "The two representative orthogonal receptors, PDGFRα Y206S and V242K, were evaluated for their efficacy to neutralize virus infection." (PMID 32559251, 2020). "Hs578T cells underwent a productive viral infection when exposed to HCMV, as did HEL299 fibroblasts that depended on the expression of PDGFRA." (PMID 34575976, 2021).
amyotrophic lateral sclerosis (4 papers, 2017 to 2021). Amyotrophic lateral sclerosis (ALS) is a neurodegenerative disease characterized by progressive muscular paralysis reflecting degeneration of motor neurons in the primary motor cortex, corticospinal tracts, brainstem and spinal cord. "In addition, inhibition of the PDGF-CC/PDGFRα axis has been shown to reduce BBB dysfunction, and has beneficial therapeutic effects in animal models of spinal cord injury (SCI), multiple sclerosis (MS), traumatic brain injury (TBI), seizures and amyotrophic lateral sclerosis (ALS)." (PMID 30021009, 2018).
brainstem gliomas (4 papers, 2015 to 2025). "Other mutations that have been reported in adult brainstem glioma, such as mutations in PDGFRA, PIK3CA, and PPM1D, are also potentially targetable with drugs that are either already commercially available or in development." (PMID 27556016, 2016). "Demonstration of PDGFRA amplification as the most common CNA among pediatric HGG, and the association of histone H3.3 mutation in malignant pediatric brain-stem glioma with PDGFRA amplification, identified PDGFRα and its signaling pathways as likely integral to the malignant behavior of some tumors." (PMID 25732621, 2015). "As PDGFRα expression is elevated in pediatric high-grade brainstem glioma patients, the researchers infected RCAS-PDGF into the posterior fossa of neonatal Ntv-a mice within 72 h of birth, resulting in the formation of low-grade brainstem gliomas." (PMID 41154198, 2025).
bronchopulmonary dysplasia (4 papers, 2018 to 2022). Bronchopulmonary dysplasia is a chronic respiratory disease that results from complications related to lung injury during the treatment of infant acute respiratory distress syndrome in low-birth-weight premature infants or from abnormal lung development in older infants. "Aberrant PDGFRA activity have been linked to a large number of diseases, including adult diseases such as fibrosis and cancer, and pediatric diseases such as bronchopulmonary dysplasia (BPD)." (PMID 30178747, 2018). "In lungs of preterm infants who died with bronchopulmonary dysplasia, PDGFRa is reduced and the number of proliferative AT2s is diminished, indicating that an evolutionarily conserved mechanism governs pAT2 behavior during alveologenesis." (PMID 35385750, 2022). "Thus, a transient downregulation in PDGFRα signaling during early infancy produces long-lasting changes in lung architecture and alveolar stretch ability to cause emphysematous dysfunction, reminiscent of bronchopulmonary dysplasia (BPD)." (PMID 32295602, 2020).
chronic myelomonocytic leukemia (4 papers, 2013 to 2022). A myelodysplastic/myeloproliferative neoplasm which is characterized by persistent monocytosis, absence of a Philadelphia chromosome and BCR/ABL fusion gene, fewer than 20 percent blasts in the bone marrow and blood, myelodysplasia, and absence of PDGFRA or PDGFRB rearrangement. "In contrast to rearrangements involving PDGFRB, the FIP1L1- PDGFRA rearrangement is exceedingly rare in the setting of chronic myelomonocytic leukemia." (PMID 24669761, 2014).
cleft palate (4 papers, 2016 to 2022). Cleft palate is a fissure type embryopathy that affects the soft and hard palate to varying degrees. "PDGFRA mutant mice developed cleft palate due to a defect of the palatal shelf growth associated with the reduced extracellular matrix production." (PMID 34897389, 2022). "Impairment of platelet-derived growth factor (PDGF) receptor α (PDGFRA) and the resultant mutation in the 3′ untranslated region (UTR) of the PDGFRA gene (c.*34G > A) is associated with cleft palate in humans, mice, and zebrafish." (PMID 35370658, 2022). "PDGFRA encodes a platelet-derived growth factor receptor that has been linked with congenital neural tube defects (NTDs) and isolated cleft palate." (PMID 29546377, 2018).
diffuse intrinsic pontine glioma (4 papers, 2019 to 2023). A neuroglial tumor that arises from the middle portion of the brain stem. "DNA analysis of a diffuse intrinsic pontine glioma (DIPG), TH02_0092_S01, revealed copy number gains of KDR (OMIM 191306), KIT (OMIM 164920), and PDGFRA, located on 4q12." (PMID 31651965, 2019).
Ewing sarcoma (4 papers, 2012 to 2017). A small round cell tumor that lacks morphologic, immunohistochemical, and electron microscopic evidence of neuroectodermal differentiation. "Additionally, EWS-FLI1 directly upregulated PDGF-C expression, which in turn activated the PDGFRα pathway in Ewing sarcoma." (PMID 28511645, 2017).
glioneuronal tumors (4 papers, 2020 to 2025). "Our results provide valuable insights into the molecular mechanism underlying the activation of PDGFRα by the K385I/L mutations, highlighting their potential as actionable targets in the treatment of myxoid glioneuronal tumors." (PMID 38532028, 2024).
ischemia (4 papers, 2012 to 2023). A hypoperfusion of the BLOOD through an organ or tissue caused by a PATHOLOGIC CONSTRICTION or obstruction of its BLOOD VESSELS, or an absence of BLOOD CIRCULATION. "Definitively establishing that FAPs are responsible for the increased skeletal muscle adiposity in the setting of ischemia would likely require a genetic approach, such as ablation of PDGFRα+ FAPs." (PMID 36937923, 2023). "A clear decrease in O1- and PDGFRα-immunoreactivity in cells aligned parallel to axon bundles was observed in diabetic eyes submitted to ischemia pulses." (PMID 23284834, 2012).
leiomyoma (4 papers, 2009 to 2025). A well-circumscribed benign smooth muscle neoplasm characterized by the presence of spindle cells with cigar-shaped nuclei, interlacing fascicles, and a whorled pattern. "The leiomyoma was immunohistochemically positive for vimentin, α-smooth muscle actin, and desmin (1 case), but negative for cytokeratins, CD34, KIT, and PDGFRA." (PMID 27956961, 2009).
liposarcoma (4 papers, 2015 to 2025). A usually painless malignant tumor that arises from adipose tissue. "While both liposarcoma cell lines (DDLS and LS141) showed high levels of IGF1-R expression, only MPNST cell line showed significant levels of PDGFRα expression." (PMID 26675259, 2016).
ovarian tumor (4 papers, 2014 to 2026). "When present, PDGFRα may be stimulated in an autocrine loop by ovarian tumors co-expressing PDGF-AB." (PMID 30591028, 2018).
paraganglioma (4 papers, 2012 to 2025). A benign or malignant neoplasm arising from paraganglia located along the sympathetic or parasympathetic nerves. "This immature, multipotent phenotype is supported by constitutive amplification of NOTCH signaling genes and by loss of the microRNA-200s and -34s, which control NOTCH1, ZEB1, and PDGFRA in head and neck paraganglioma cells." (PMID 30813557, 2019). "Indeed, it was shown that mutations in SDHA account for around 30% of all KIT/PDGFRA-WT GIST, while being responsible for <1% of all pheochromocytoma and paraganglioma cases (PPGL), as opposed for example to SDHB that accounts for about 10% of all PPGL." (PMID 35059314, 2021). "The best known association between SDH complex II germline mutations and other tumors is represented by the Carney–Stratakis syndrome (or dyad) which is characterized by the occurrence of KIT and PDGFRA WT GIST and paraganglioma." (PMID 22974104, 2012). "Additionally, no somatic drivers were identified in the pheochromocytoma and paraganglioma, nor were any pathogenic variants in KIT or PDGFRA detected in the GIST." (PMID 40242210, 2025).